REN (renin)
Diseases named in the same sentence as REN in open-access papers (continued):
Sharing a sentence is not in itself a finding about the gene and the disease.
Moyamoya disease (1 paper, 2022). Moyamoya disease (MMD) is a rare intracranial arteriopathy involving progressive stenosis of the cerebral vasculature located at the base of the brain causing transient ischemic attacks or strokes. "Plasma renin activity could be elevated in laboratory tests, and in an earlier study six pediatric patients with moyamoya disease combined with VRH had elevated plasma renin." (PMID 36090342, 2022).
Neonatal sepsis (1 paper, 2024). Systemic inflammatory response to infection in newborn babies. "Furthermore, diminished CXCL-10 and renin, as well as non-significant trends towards decreased biomarker concentrations for KIM-1, TIMP-1, and osteopontin were noted after CEF and PTX treatment, suggesting that addition of PTX to antibiotics may reduce acute kidney injury during neonatal sepsis." (PMID 39963236, 2024).
nephrogenic diabetes insipidus (1 paper, 2024). Nephrogenic diabetes insipidus (NDI) is characterized by polyuria with polydipsia, recurrent bouts of fever, constipation, and acute hypernatremic dehydration after birth that may cause neurological sequelae. "For instance, clarifying the role of cellular plasticity and renin expression may improve our understanding of adaptive kidney responses or diseases such as nephrogenic diabetes insipidus, metabolic acidosis, and age-related renal fibrosis." (PMID 39273497, 2024).
neuroendocrine tumours (1 paper, 2020). "The majority of monogenic syndromes involve the renin-angiotensin-aldosterone system and the adrenal glucocorticoid pathway, and a smaller fraction are due to rare neuroendocrine tumours of the adrenal glands and the sympathetic and parasympathetic paraganglia." (PMID 32389342, 2020).
normal tension glaucoma (1 paper, 2020). "The purpose of this study was to investigate the function of the renin–angiotensin–aldosterone system (RAAS) in normal tension glaucoma (NTG) patients by measuring the level of renin and angiotensin II (AngII) in the plasma." (PMID 33256138, 2020).
nutcracker syndrome (1 paper, 2015). "Although systemic hypertension is not considered in the clinical manifestation of the nutcracker syndrome, some reports have described the presence of renin dependent hypertension in the patients with nutcracker syndrome." (PMID 26448765, 2015).
open-angle glaucoma (1 paper, 2020). Chronic outflow obstruction of the eye's drainage canals that can lead to increased internal eye pressure and optic nerve damage. "Our objective was to evaluate the renin,angiotensinconverting enzyme 1, and angiotensin-converting enzyme 2activities in aqueous humor and blood samples of patients with and withoutprimary open-angle glaucoma." (PMID 32756783, 2020). "As timolol eye drops were used by most of theprimary open-angle glaucoma patients, we propose that a large sample ofwashed-out patients should be studied in the future to discriminate theinvolvement of b-blocker treatment in the aqueous humor renin activity." (PMID 32756783, 2020).
ovarian diseases (1 paper, 2025). "As shown in our results and previous studies, PCOS is frequently associated with abnormal RAS activity in non-iatrogenic ovarian diseases, particularly in terms of total renin concentrations, ACE activity, and AngII levels." (PMID 40425574, 2025).
paraganglioma (1 paper, 2025). A benign or malignant neoplasm arising from paraganglia located along the sympathetic or parasympathetic nerves. "Markedly elevated plasma renin and urinary normetanephrine, along with a retroperitoneal mass, suggested paraganglioma." (PMID 40587311, 2025). "Given the markedly elevated plasma renin and urinary normetanephrines in the context of persistent hypertension, a contrast‐enhanced CT urography (CTU) was performed, which identified a hypervascular mass in the right retroperitoneal space, raising suspicion for a paraganglioma." (PMID 40587311, 2025).
paroxysmal AF (1 paper, 2024). "Initial renin–angiotensin–aldosterone system (RAAS) activation in patients with renal impairment may itself be arrhythmogenic, where oxidative stress mediates changes in cellular ion channels, resulting in paroxysmal AF." (PMID 38793116, 2024).
periodontal disease (1 paper, 2019). "The aim of this study was to characterize the role of local RAS (renin–angiotensin system) in the inflammatory response of normal (N) and diabetic (D) mice with periodontal disease (PD)." (PMID 31333451, 2019).
peripartum cardiomyopathy (1 paper, 2021). Peripartum cardiomyopathy (PPCM) is an idiopathic, potentially fatal form of dilated cardiomyopathy that develops during the final month of pregnancy or within five months after delivery. "Women with a previous diagnosis of peripartum cardiomyopathy may want to try to become pregnant again and elect to stop taking renin-angiotensin-aldosterone blockers." (PMID 34119469, 2021).
pneumonitis (1 paper, 2019). An inflammatory process affecting the lung parenchyma. "For example, it has been revealed that abnormal upregulation of renin-angiotensin system plays a key role in both pneumonitis and fibrosis." (PMID 31366142, 2019).
radiculopathy (1 paper, 2024). Disease involving a spinal nerve root (see spinal nerve roots) which may result from compression related to intervertebral disk displacement; spinal cord injuries; spinal diseases; and other conditions. "Additionally, suggestive links were found between vasodilator antihypertensives and reduced radiculopathy risk, and both alpha-adrenoceptor blockers and renin inhibitors possibly decreasing dorsalgianas risk (unspecified dorsalgia)." (PMID 39268473, 2024).
renal angiomyolipoma (1 paper, 2024). "Although the exact mechanism is unclear, the positive renin antibody indicated that renin was being produced by renal angiomyolipoma." (PMID 39650950, 2024).
renal tubular acidosis (1 paper, 2023). A group of genetic disorders of the kidney tubules characterized by the accumulation of metabolically produced acids with elevated plasma chloride, hyperchloremic metabolic acidosis. "The abnormal expression of KIT and its correlated DEGs might be a signal related to kidney failure disease, smoking behaviors, renal tubular acidosis, distal, autosomal recessive, pseudohypoaldosteronism, type II and hyperactive renin-angiotensin system disease." (PMID 37808589, 2023).
retinal diseases (1 paper, 2024). "As a result, dysregulation of renin-angiotensin system may also lead to inflammation and oxidative stress impacting the pathogenesis and progression of both kidney and retinal diseases." (PMID 37869020, 2024).
retroperitoneal fibrosis (1 paper, 2025). "Increasing evidence suggests that the molecular mechanisms underlying IgG4-TIN may be associated with retroperitoneal fibrosis, activation of the renin–angiotensin system, and microbial dysbiosis." (PMID 40718410, 2025).
scleroderma (1 paper, 2025). Scleroderma is a rare autoimmune connective tissue disorder characterized by abnormal hardening of the skin and, sometimes, other organs. "The much clearer correlation between renin and PlGF suggests that renal ischemia induced by the endothelial lesions of scleroderma reflects what triggers PlGF synthesis, not clearance." (PMID 40225361, 2025).
shigellosis (1 paper, 2021). Shigellosis is a bacterial infection leading to dysentery and is caused by Shigella, which are small, ubiquitous Gram-negative bacteria belonging to the enterobacteria family. "We obtained five pathways, including the mammalian target of rapamycin (mTOR) signaling pathway, renin–angiotensin system, protein digestion and absorption, mineral absorption, central carbon metabolism in cancer, and Shigellosis." (PMID 34149613, 2021).
stenosis (1 paper, 2022). "Renal artery stenosis, renal infarction, rarely renin tumours, and any renal damage can result in a secretion of renin and secondary hyperaldosteronism." (PMID 35054115, 2022).
Stillbirth (1 paper, 2024). Death of the fetus in utero after at least 22 weeks of gestation. "Since then, several studies have documented four pregnancies with renin-secreting tumors; however, all reported pregnancies have resulted in stillbirth, premature delivery, or the decision to terminate the pregnancy early, owing to uncontrolled blood pressure despite antihypertensive drugs." (PMID 39650950, 2024).
sympathetic paraganglioma (1 paper, 2025). A benign or malignant paraganglioma arising from the chromaffin cells of the paraganglia that are located along the sympathetic nerves. "However, when considered alongside markedly elevated plasma renin and a hypervascular retroperitoneal mass, this finding supported the diagnosis of sympathetic paraganglioma." (PMID 40587311, 2025).
synthesis (1 paper, 2022). "The related pathways of the involvement of FSH in a renin synthesis disorder have not been evaluated." (PMID 35501878, 2022).
tendinopathy (1 paper, 2018). "In addition, other systemic agents have caused tendinopathy; they include amlodipine, anabolic steroids, antiretrovirals, isotretinoin, renin-angiotensin II receptor antagonists, rituximab, and sitagliptin." (PMID 30915263, 2018).
treatment-resistant hypertension (1 paper, 2025). "All patients presented with treatment-resistant hypertension and elevated aldosterone-to-renin ratios." (PMID 41517422, 2025).
ulcerative colitis (1 paper, 2016). An inflammatory bowel disease involving the mucosal surface of the large intestine and rectum. "However, ACE-I, renin, DPP-IV and PAF-AH are enzymes that are also present in the gut, and recent evidence suggests that inhibition of these enzymes can impact positively on gut health and may help to prevent necrosis, ulcerative colitis and other inflammatory disorders of the human gut." (PMID 27043546, 2016).
uterine corpus endometrial carcinoma (1 paper, 2020). A endometrial carcinoma (disease) that involves the body of uterus. "Angiotensin-converting enzyme 2 (ACE2) is a member of the renin-angiotension system, however, the correlation between ACE2 and prognosis in UCEC (Uterine Corpus Endometrial Carcinoma) and KIRP (Kidney Renal Papillary Cell Carcinoma) is not clear." (PMID 32339157, 2020).
vascular insufficiency (1 paper, 2023). "Thus, renin secretion may be induced by a reduction in the microvascular circulation of the stria vascularis in SSNHL to recover from vascular insufficiency and activate the RAA system." (PMID 38516543, 2023).
cardiovascular disease (269 papers, 2006 to 2026). "A well-designed study has added new evidence regarding the association between suppressed renin, high aldosterone levels, and cardiovascular disease." (PMID 39877848, 2024). "Vitamin D impacts the renin–angiotensin–aldosterone system which is involved with blood pressure regulation and volume homeostasis, and low levels are linked to cardiovascular disease." (PMID 37892510, 2023). "Cardiovascular disease is the leading cause of death worldwide, while the renin-angiotensin system is the main hormone cascade system involved in the pathophysiology of cardiovascular disease." (PMID 36897667, 2023). "The renin-angiotensin system (RAS) is involved in cardiovascular disease risk factors and is an enzymatic pathway that promotes cardiovascular disease (CVD) and the progression of cardiovascular disease." (PMID 36401332, 2022). "Angiotensin II receptor type 1 (AGTR1) is a significant effector of the renin-angiotensin-aldosterone system, which is associated with cardiovascular diseases, especially cardiac remodeling." (PMID 34765659, 2021). "ACE2 is part of the renin-angiotensin system and is also associated with lung and cardiovascular disorders and inflammation." (PMID 32369402, 2020). "On the other hand, several studies have shown that increases of renin, aldosterone, and catecholamines are all associated with increased cardiovascular disease events and mortality." (PMID 31438636, 2019). "Vitamin D has been associated with renal and cardiovascular diseases because of its effects on oxidative stress, lipid metabolism and renin-angiotensin-aldosterone system (RAAS)." (PMID 25048368, 2014). "1,25-dihydroxyvitamin D could alleviate chronic inflammatory states,and regulate the renin–angiotensin system, helping to lower blood pressure and reduce the risk of cardiovascular disease." (PMID 40626228, 2025). "Moreover, an association between (pro)renin gene polymorphisms and cardiovascular disease has been reported." (PMID 38255922, 2024). "More recently, one study clarified whether renin-independent aldosteronism (i.e., subclinical PA), which fails to diagnose PA using current diagnostic criteria, is involved in cardiovascular disease." (PMID 39877848, 2024). "It is shown that SARMs may increase the risk of cardiovascular diseases through implications on the renin–angiotensin system, smooth muscle cells, sympathetic nervous system, lipid profile, inflammation, platelet activity, and various other factors." (PMID 37571268, 2023). "Low birth weight (LBW) is associated with increased risk of adult cardiovascular disease and this association may be partly a consequence of early programming of the renin–angiotensin system (RAS)." (PMID 25649246, 2015). "In our model, which employs endogenous activation of the renin-angiotensin system due to renal artery stenosis we find that db/db mice are more susceptible to both renal and cardiovascular disease than WT mice, despite similar elevation in systolic blood pressure." (PMID 26925344, 2016). "Historically, the pharmacologic therapy of cardiovascular disease has centered around blood pressure control, insulin and cholesterol management, the inhibition of the renin–angiotensin system, and catecholamine blockade." (PMID 40558547, 2025). "For example, miR-483 targets the renin–angiotensin–aldosterone system exclusively in cardiovascular disease, defining its blood pressure regulatory role." (PMID 41463366, 2025). "Extensive evidence supports the concept that high renin levels predict future cardiovascular disease and death, particularly in hypertensive patients." (PMID 40959573, 2025). "Patients with AKI are particularly susceptible to renin–angiotensin–aldosterone system (RAAS) disruption, which can cause inadequate blood pressure control, cardiovascular disease, fluid imbalance, electrolyte abnormalities and CKD." (PMID 40583865, 2025).
cardiovascular disease (continued). "The renin‐angiotensin system (RAS) is an important regulator of cardiovascular disease and plays an important role in vascular pathophysiology." (PMID 40510524, 2025). "In fact, the renin-angiotensin system plays a fundamental role in the regulation of blood pressure, electrolytes and blood volume, and in the pathophysiology of cardiovascular diseases." (PMID 40218994, 2025). "ACE1, on the other hand, is part of the same renin–angiotensin system; the I/D polymorphism in ACE1 has been variably linked to cardiovascular disease risk and inflammation." (PMID 40563839, 2025). "The medications most frequently named by older adults with polypharmacy for deprescribing were those usually used in the treatment or prevention of cardiovascular diseases (diuretics, lipid-modifying agents, and agents acting on the renin-angiotensin system)." (PMID 39928337, 2025). "The renin–angiotensin system contributes to a high spectrum of cardiovascular disorders and is essential for maintaining normal cardiovascular homeostasis." (PMID 38397857, 2024). "Overactivation of the classical renin–angiotensin system is one of the most important pathophysiological mechanisms in the progression of cardiovascular diseases." (PMID 38397857, 2024). "Ang II is a pivotal factor in the pathophysiology of cardiovascular diseases and serves as the main effector of the renin–angiotensin system." (PMID 38673809, 2024). "Oestrogen is protective against cardiovascular disease, possibly due to its role in lowering blood pressure via regulation of the renin–angiotensin–aldosterone system." (PMID 37269199, 2023). "When patients are dehydrated or have certain cardiovascular diseases occurring, sympathetic excitation and activation of the renin–angiotensin–aldosterone system can increase the reabsorption of urea nitrogen by the body." (PMID 38114922, 2023). "ADM can regulate myocardial protection by disrupting mitochondrial metabolism and lowering the renin-aldosterone system levels in cardiovascular diseases." (PMID 36978012, 2023). "It merges into the idea that the role of the renin-angiotensin-aldosterone system and the sympathetic nervous system in the immune response is contradictory in patients with cardiovascular disease." (PMID 36778208, 2023). "As the only enzyme known to cleave angiotensinogen and the rate-limiting enzyme of the renin-angiotensin system, plasma renin can increase the synthesis of angiotensin II and aldosterone, which plays a critical role in cardiovascular disease." (PMID 37383707, 2023). "The renin-angiotensin system (RAS) is a major classic therapeutic target for cardiovascular diseases." (PMID 36824459, 2023). "IVF-produced female offspring showed the altered expression of the renin–angiotensin system in the myocardium, which regulates the blood pressure and is known to play a role in the pathogenesis of cardiovascular disease." (PMID 37065763, 2023). "The AGTR1 gene mediated by the renin–angiotensin system is crucial to the pathophysiology of cardiovascular diseases." (PMID 36831718, 2023). "ACE2 regulates the renin-angiotensin system and exerts a protective effect against severe organ damage but ACE2 gene polymorphisms were associated with cardiovascular diseases." (PMID 37986157, 2023). "Angiotensin-converting enzyme 2 (ACE2) works as an endogenous counter-regulator of the renin-angiotensin system, which has pivotal roles in preventing both cardiovascular disease (CVD) and inflammation." (PMID 35155493, 2022). "This suggests that increased FSH levels are correlated with known cardiovascular disease (CVD) risk factors and reveals the critical roles of FSH in renin activity." (PMID 35501878, 2022). "Angiotensin converting enzyme 2 (ACE2) is an endogenous negative regulator of the renin-angiotensin system, a key factor in the development of cardiovascular disease (CVD)." (PMID 36143280, 2022).